EGFR (epidermal growth factor receptor)
Diseases named in the same sentence as EGFR in open-access papers (continued):
Sharing a sentence is not in itself a finding about the gene and the disease.
tumor (continued). "In the second model, slow cycling DTP cells initially survive anti-EGFR treatment and later start to undergo cell division and acquire de novo resistance mechanisms, including driver and non-driver resistance mechanisms in a subset of persister cells, as recently shown for a number of tumor types." (PMID 34271981, 2021). "In addition, previous studies found that high tumor mutation burden (TMB) and PD-L1 expression, which were considered to predict better outcomes from immunotherapy, were more likely presented in patients with relatively shorter PFS to EGFR-TKI." (PMID 33777802, 2021). "Therefore, it was concluded that tumor-derived exosomal circRNA_ 102481 could contribute to EGFR-TKIs resistance via the microRNA-30a-5p/ROR1 axis in NSCLC." (PMID 33952725, 2021). "In two of the EGFR patients included, along with the disease′s course, there were no detectable mutations regardless of the presence and quantity of cfDNA, representing the absence of mutant variants, and eventually non-shedding DNA from the tumour." (PMID 34440680, 2021). "Furthermore, follow-up CT scans showed SD until the patient quit therapy, which suggested that the combination therapy of afatinib and bevacizumab could inhibit the tumor growth in EGFR-mutant patients with ERBB2 amplification." (PMID 33663050, 2021). "Furthermore, TAMs also promoted tumor progression under hypoxia by interacting with corresponding receptors, such as EGFR- and FGFR2-promoting tumor cell proliferation, CD44-promoting tumor invasiveness, and VEGF-inducing angiogenesis to increase invasion ability of tumor cells." (PMID 34956900, 2021). "Tumor-specific antibody drug conjugate Depatux-M which consists of an EGFR antibody (ABT-806) linked to monomethyl auristatin F provided positive results in recurrent EGFR-amplified GBM, but not in phase III trial due to unstable EGFR expression." (PMID 34715891, 2021). "We also observed a substantially lower level of CXCL13 expression in EGFR-MT than in EGFR-WT tumor, which further supports the hypothesis that CXCL13-producing TFH-like cells contribute to the anti-PD-1 response through recruiting B cells to functional TLS in tumors." (PMID 34663810, 2021). "However, the presence of LncRNA H19 SNP rs2107425 on the tumor T status is significant even in the enrolled study population with different EGFR phenotype, which implies the influence of LncRNA H19 SNP rs2107425 on LADC disease course cannot be overlooked especially for those with EGFR wild-type." (PMID 33799753, 2021). "However, tumor heterogeneity is a major cause of treatment failure, illustrated by the clonal expansion of resistant subclones with acquired RAS mutations during anti-EGFR treatment." (PMID 34470666, 2021). "EGFR also exists in urinary exosomes, which may be a new kind of indicator of tumor progression." (PMID 33922480, 2021). "Tumor tissue collected by re-biopsy was analyzed by next generation sequencing with an OncoAim Lung cancer targeting gene detection kit (Singlera Genomics, Inc., Shanghai, China) and revealed an acquired ERBB2 amplification (ERBB2_amp) in conjunction with EGFR 19 deletion mutation." (PMID 33663050, 2021). "Here, using single cell sequencing, the authors find that tissue resident memory CD8+ T like cells are reduced in the immune landscape of EGFR mutant tumours in comparison to wild type tumours and the presence of these cells may predict response to immunotherapy." (PMID 34663810, 2021). "This correlation was enhanced in patients with conserved miR-let-7a-binding sequence in KRAS-coding mRNA, suggesting that patients with high tumor expression of miR-let-7a may benefit from an anti-EGFR therapy irrespective of KRAS mutational status." (PMID 34208056, 2021). "However, the amino acid starvation culture or the knockdown of LAT1 in EGFR expressing tumor cells could induce necroptosis to enhance the cytotoxic effect of gefitinib, an EGFR tyrosine kinase inhibitor." (PMID 34681614, 2021).
tumor (continued). "Furthermore, we divided the EGFR-mutant NSCLC into a low ΔCT value and a high ΔCT value to explore whether the ΔCT value of the tumor sample could be a predictor for the efficacy of EGFR-TKIs in EGFR-mutant NSCLC patients." (PMID 34692766, 2021). "The free integrin associates with RTKs (e.g., EGFR, HER2, c-Met, Ron kinase), resulting in phosphorylation of tyrosines in the β4 integrin cytoplasmic domain and activation of signaling effectors that drive proliferation, survival and invasion of the tumor cells." (PMID 34778093, 2021). "Given the special role of coordinate downregulation of both direct (epidermal growth factor receptor) and indirect (phospho-Akt) growth-promoting targets, miR-7-5p performs a tumor-suppressor function, which ultimately serves to impede the development of tumor in vitro and vivo." (PMID 33422052, 2021). "For example, in patients with a low abundance of EGFR mutations, tumor clones without EGFR mutations may dominate in the primary tumors." (PMID 34034713, 2021). "Similarly, the phosphorylation of EGFR’s serine 229, by AKT, also promotes the nuclear translocation of EGFR, which acts as a co-transcription factor of multiple genes, regulating cell proliferation and tumor angiogenesis, resulting in enhanced drug resistance and poor patient outcomes." (PMID 34445495, 2021). "Therefore, EGFR is considered to be a signal transducer, as well as a tumor marker, in OSCC cells." (PMID 33449240, 2021). "Instead, we speculate that anti-EGFR/VEGFR2 BsAb exerts its anti-tumor activity in our in-vivo mouse study via inhibition of EGFR signaling and disruption of autocrine and/or paracrine mechanisms modulated by VEGF/VEGFR2, which further supports our findings from cellular models." (PMID 33804477, 2021). "Accordingly, phosphorylated STAT3 expression could also be used as a guide to measure EGFR activity and identify patients that may not necessarily have EGFR mutations, but still depend on EGFR signaling for tumor cell proliferation and survival." (PMID 34944848, 2021). "Considering that an acidic tumor microenvironment crucially impairs immune effector cell activation and therefore anti-tumor immune responses, we hypothesized that the efficacy of EGFR-targeting antibody-based therapy can be increased by metabolic reprogramming of the tumor itself." (PMID 34830971, 2021). "For example, aberrant EGFR signaling in NSCLC cells upregulates PDL1 expression through activation of the IL6/JAK/STAT3 pathway, while combined STAT3 and PDL1 inhibition renders tumor cells more susceptible to cytotoxic T-cell mediated killing and delays tumor growth in mice." (PMID 34944848, 2021). "The discordance of EGFR mutation between sputum and surgical specimens might be due to the absence of tumor cells in the sputum." (PMID 33757469, 2021). "However, these same pathways are likely to be induced by oncolytic recombinant gene therapy vectors targeting EGFR-overexpressing tumor, where they may have unanticipated consequences." (PMID 35083168, 2021). "However, in these studies, it remains unclear as to whether pain relief was attributable to the effects of EGFR therapy on the tumor or a direct effect of EGFR therapy on neuropathic pain signaling." (PMID 34054523, 2021). "Moreover, PTK7 regulates tumor metastasis and collagen fibril organization via EGFR-Akt pathway." (PMID 34367983, 2021). "The majority of driver mutations are targetable by the EGFR tyrosine kinase inhibitors (TKIs) (e.g. gefitinib, erlotinib, afatinib, and osimertinib in EGFR-mutant NSCLC; crizotinib, ceritinib, brigatinib, lorlatinib, and alectinib in ALK rearranged tumours; crizotinib in ROS1 rearranged disease)." (PMID 34094913, 2021).
tumor (continued). "Likewise, studies focusing solely on visualization of tumor specific molecular markers, amongst these IDH (isocitrate dehydrogenase gene) mutation, EGFR (Epidermal Growth Factor) gene amplification and the proliferation biomarker Ki-67, were not included despite promising results in earlier studies." (PMID 33806195, 2021). "In the in vivo tumor microenvironment, EGFR mutation may not be an independent risk factor for recurrence because of attenuated immunosuppression in connection with the tendency for low PD-L1 expression levels in cells with EGFR mutations." (PMID 34471191, 2021). "To develop an assay that could be used to evaluate clinical formalin-fixed paraffin-embedded (FFPE) tumor specimens, we evaluated EGFR:MET transcript ratios through BaseScope, an RNA-based in situ hybridization assay in which fluorescent signal area acts as a surrogate for RNA transcript expression." (PMID 34516823, 2021). "Clinically actionable PIK3CA mutations in exons 9 and 20 have been previously found in the EGFR-mutant tumours of patients with acquired resistance to first- and second-generation EGFR-TKIs5,28–30 and could have been selected as a result of TKI selective pressure." (PMID 33741979, 2021). "Therefore, blocking EGFR signaling has the potential to reverse or slow tumor progression." (PMID 33787673, 2021). "Interestingly, a recent publication revealed a direct, positive correlation between EGFR mutation status and a so called “lymphocyte depletion” phenotype of these tumours, in which there was a pronounced lack of tumor-infiltrating CD8 T-cells." (PMID 35052732, 2021). "Thus, EGFR-expressing cancer cells might be more vulnerable by altered Na+ concentrations than non-tumor cells with lower EGFR expression levels." (PMID 34025398, 2021). "It suggested that for patients with advanced NSCLC who could not obtain tumor tissue, EGFR gene mutations can be detected by pleural effusion samples instead of tumor tissue." (PMID 35049681, 2021). "To explore whether KTN1 may specifically regulate EGFR protein levels in tumor cell lines, we transfected siKTN1 and siKTN1# into the human immortalized keratinocytes cell line HaCaT, in addition, KTN1mut was also transfected into the cell line to demonstrate the gene-specific of siKTN1." (PMID 34689164, 2021). "Furthermore, the introduction of a first immunocompromised version of the AlbuMus allows accurate anti-tumour investigations of an anti-EGFR x anti-CD3 bispecific albumin fusion in BRAF-mutated tumours non-respondent to standard anti-EGFR monoclonal therapies." (PMID 33686177, 2021). "Therefore, we firmly speculate that the interactions between the two signaling pathways underlie the need to block both these pathways to achieve a significant inhibition of tumor growth, especially in EGFR-TKI resistant NSCLC." (PMID 34210314, 2021). "Therefore, the inhibition of EGFR signaling might reduce PD-L1 expression in the tumor cells, further reducing PD-L1–mediated tumor evasion." (PMID 34211836, 2021). "Therefore, we hypothesized that MYH10 exerts its tumour‐suppressive role by reducing the activation of EGFR pathway." (PMID 34738311, 2021). "In addition, and to the best of our knowledge, no studies have evaluated radiomic analysis in the context of complementing liquid biopsy-based assessment, which is another promising non-invasive tool for characterizing tumor heterogeneity when predicting EGFR-TKIs response." (PMID 33976268, 2021). "Moreover, epidermal growth factor receptor (EGFR) also constitutes an essential factor in normal epithelial development as well as in the proliferation, motility, survival, and metastasis of tumor cells, and its expression has been associated with NSCLC aggressiveness." (PMID 33947159, 2021). "However, its effectiveness varies between tumor location, stage, and EGFR alteration." (PMID 33919702, 2021).
tumor (continued). "EGFR, for example, is highly expressed in the healthy brain, and therefore oHSVs retargeted to EGFR, like KNE, could potentially cause harmful off-tumor effects." (PMID 34578259, 2021). "For example, the aptamers human epidermal growth factor receptor-2, epidermal growth factor receptor (EGFR), and folate have been conjugated to 3WJ-pRNA for the targeted delivery of RNAs to tumor tissues, and the specifically delivered RNAs significantly regressed tumor growth and improved survival." (PMID 35002692, 2021). "Besides, Cetuximab-IRDye800 targeting EGFR is an adequate tracer in several tumor types." (PMID 33535618, 2021). "In addition, when used in combination with EGFR inhibition, it is possible to taper the dose of prednisone after initially starting at a higher dose without a loss of tumor inhibition." (PMID 34853306, 2021). "In Western countries, EGFR mutations are present in 10–35% of NSCLC cases, but the prevalence of these mutations is not uniform among populations; it tends to be more prevalent in females, non-smokers, and patients with bronchioloalveolar features in tumor specimens." (PMID 34940073, 2021). "In addition to EGFR, c-Met and Akt reduction, this study also found that combination treatment significantly lowered tumour growth on xenograft mice models and more importantly, 60 mg/kg of gefitinib combined with 1 g/kg of curcumin showed comparable results to 120 mg/kg of gefitinib." (PMID 34867402, 2021). "Besides enhancement of CRC goblet cell differentiation, both therapeutic regimens, GFHPD or anti-EGFR antibody therapy, strongly dampened colonic PD-L1 and splenic T-cell specific PD-1 immune checkpoint expression, presumably promoting improved anti-tumor immune responses." (PMID 34830971, 2021). "For example, β1 integrin silencing in human NSCLC A549 cells showed a defective activation of the EGFR signaling cascade, resulting in enhanced sensitivity to Gefitinib and cisplatin, reduced migration, and invasive behavior, and decreased in vitro proliferation and in vivo tumor growth." (PMID 34976811, 2021). "Moreover, post hoc biomarker analyses of clinical trials has suggested that RAS status in circulating tumor DNA (ctDNA) has a high probability to select patients who could benefit from anti-EGFR mAb rechallenge." (PMID 34098908, 2021). "Given that the proportion of tumor-infiltrating TRM-like cells decrease in EGFR-MT lung tumors, which tends to show poor response to anti-PD-1 immunotherapy, we hypothesized that the relative abundance of TRM-like cells in the tumor by itself could predict the anti-PD-1 response." (PMID 34663810, 2021). "Notably, the combination of Acalabrutinib and Osimertinib exhibited significant tumor growth inhibition in vivo, indicating that Acalabrutinib could potentiate mice-bearing EGFR TKI-resistant tumors to Osimertinib treatment." (PMID 34315851, 2021). "Therefore, EGFR proteins overexpression leads to increased tumor proliferation." (PMID 34711249, 2021). "The group of repebodies with a broad range of affinities were expected to be ideal for investigating the affinity-based differences in tumor localization (with the uncontrolled variables excluded) because they shared a strong sequence identity (>95%) and bound a common epitope on EGFR." (PMID 33615202, 2021). "Hence, TGFβ inhibition strategies may be considered for tumours overexpressing wt or mutant forms of the EGFR." (PMID 35052732, 2021). "Furthermore, EGFR in EVs correlates with the ki-67 labeling index in tumor tissue." (PMID 34638714, 2021). "In the present study, PD-L1 expression in the tumor was associated with PFS and objective response, indicating that ICIs should not be thoroughly excluded from candidate therapeutic strategies for NSCLC patients with EGFR mutation or ALK fusion, especially in cases with high PD-L1 expression." (PMID 35008669, 2021). "These alterations may be necessary to drive tumor progression in EGFR‐dependent tumors." (PMID 33225515, 2021).
tumor (continued). "Based on these results, we demonstrated a new mechanism of CD151-mediated tumor progression by targeting EGFR/ErbB2 signaling pathway, by which CD151 promotes NSCLC proliferation, migration, and invasion, which may considered as a potential target of NSCLC treatment." (PMID 34108040, 2021). "EGFR mutations were detected in 6 cases, of which 2 cases had absence of tumor cells." (PMID 33828971, 2021). "Currently, there are FDA-approved inhibitors against mTOR pathway for other purposes, it is necessary to explore their efficacy to reverse anti-EGFR resistance in these tumours and looking for markers to elucidate which patients could benefit from this strategy." (PMID 34359657, 2021). "Interestingly, in vivo studies confirmed a decrease in tumor weight of xenograft models as compared to control, through the reduced expression of oncogenic proteins EGFR, Akt and cyclin D1, and enhanced caspase 3/8 activities, while being harmless to other tissues in xenograft models." (PMID 34299604, 2021). "However, mutations in oncogenic drivers such as EGFR, ALK, BRAF, or MET modify the immune tumor microenvironment and may promote anti-PD1/PD-L1 resistance." (PMID 34208111, 2021). "EGFR L858R mutation was detected in one tumour (left 10A) but not in the other tumour (left 10B)." (PMID 33707471, 2021). "The identification of driver mutations, such as somatic mutations in the epidermal growth factor receptor (EGFR) gene, and the subsequent development of EGFR tyrosine kinase inhibitors (TKIs) as targeted therapy have significantly revolutionized the treatment landscape of these tumours." (PMID 33247550, 2021). "However, the role of tumor-derived exosomal circRNA on EGFR-TKIs resistance still remains unclear yet." (PMID 33952725, 2021). "In conclusion, herein, we present results that suggest that EGFR status can be measured using ddPCR in tumour and plasma in a cost-effective way and that EGFR amplification is associated with a negative survival outcome in patients with GEA independent of treatment arm." (PMID 33199443, 2021). "Furthermore, if patients are treated with inhibitors that are ineffective towards T790M, this may select for tumour cells that may be less responsive to subsequent therapies with third-generation EGFR inhibitors." (PMID 34068816, 2021). "Within tumours, such a local, consistent activation of TGFβ may then lead to the observed non-inflamed, “lymphocyte depletion” phenotype, which is observed for tumours overexpressing the EGFR." (PMID 35052732, 2021). "Therefore, both CB2R and EGFR might be critical for initiating signaling events that lead to tumor regression." (PMID 34393784, 2021). "Tumor tissue samples were classified into three molecular subtypes according to their expression of nuclear hormone receptors (estrogen receptor (EstR), progesterone receptor (PR), and epidermal growth factor receptor (HER2)) as EstR- PR- HER2-, EstR+ PR+ HER2-, and EstR+ PR+ HER2+." (PMID 34428256, 2021). "Moreover, specific cellular binding properties on EGFR-expressing tumor cells were observed." (PMID 34759924, 2021). "The recent results of adjuvant therapy targeting activating mutations in EGFR (exon 19 deletion and L858R mutation) and of preoperative immunotherapies of early stage (I-IIIA) NSCLC open up great perspectives for the prevention of relapse and/or post-operative tumor progression." (PMID 34440926, 2021). "EGFR-targeted drugs could be considered a newly developed anti-tumor drug for NPC." (PMID 34578147, 2021). "Furthermore, EGFR stimulates Ras-dependent tumor overgrowth through canonical EGFR signaling." (PMID 34411095, 2021). "Thus, the CheckMate026 study compared nivolumab at a dose of 3 mg/kg Q2W versus platinum-based CT in patients with stage IV NSCLC with PD-L1 expression >5% in tumor cells and without EGFR- and ALK-activating mutations, but this time the results was negative." (PMID 34104805, 2021).